PFN1 (profilin 1)
Diseases named in the same sentence as PFN1 in open-access papers (continued):
Sharing a sentence is not in itself a finding about the gene and the disease.
laryngeal carcinoma (3 papers, 2014 to 2025). Carcinoma that arises from the laryngeal epithelium. "A study investigated proteomics for diagnostic biomarkers of laryngeal cancer, and four differential proteins (PFN1, NCL, CNDP2, and OGN) with expressional changes were selected to test for differential expressions." (PMID 40051609, 2025). "Furthermore, we first time show that PFN1, NCL, CNDP2 and OGN may be potential diagnostic and therapeutic targets for laryngeal carcinoma, and demonstrate that PFN1 is involved in the migration of human squamous cells." (PMID 24587265, 2014). "The data showed that PFN1 silencing inhibited the proliferation and affected the migration ability of Hep-2 cells, demonstrating that PFN1 plays an important role in human laryngeal carcinoma carcinogenesis." (PMID 24587265, 2014). "Altogether, our present data first time show that PFN1, NCL, CNDP2 and OGN are novel potential biomarkers for diagnosis and therapeutic targets for laryngeal carcinoma, and PFN1 is involved in the metastasis of laryngeal carcinoma." (PMID 24587265, 2014). "Taken together, in this study, the use of 2D LC-MS/MS identified 281 significantly differentially expressed proteins in human laryngeal carcinoma, and four differential proteins (PFN1, NCL, CNDP2 and OGN) with expressional changes were selectively verified." (PMID 24587265, 2014). "The results showed that PFN1 silencing inhibited the proliferation and affected the migration ability of Hep-2 cells, providing some new insights into the pathogenesis of PFN1 in laryngeal carcinoma." (PMID 24587265, 2014). "Moreover, it was found that PFN1 knockdown decreased the metastasis of Hep-2 cells, demonstrating that PFN1 plays an important role in metastasis of laryngeal carcinoma." (PMID 24587265, 2014). "To know whether down-regulation of PFN1 is involved in laryngeal carcinoma carcinogenesis, we knocked down PFN1 in human laryngeal carcinoma cells Hep-2, and then detected whether PFN1 knockdown decreased the proliferation and metastasis of Hep-2 cells." (PMID 24587265, 2014). "Next, semiquantitative RT-PCR was performed to detect the mRNA levels of PFN1, NCL, CNDP2 and OGN in 8 cases of paired laryngeal carcinoma tissues." (PMID 24587265, 2014). "And the results revealed that the expression of PFN1, NCL, and CNDP2 was elevated and that of OGN was reduced in laryngeal carcinoma tissue compared with the adjacent normal tissue." (PMID 24587265, 2014). "Thus, the expression of PFN1, NCL, CNDP2 and OGN were further investigated employing a large collection of human laryngeal carcinoma tissues." (PMID 24587265, 2014).
motor neuron disease (3 papers, 2018 to 2025). "Kubinski and Claus used network analysis to show that the ALS-linked protein Cu/Mn-dependent superoxide dismutase (SOD1) and profilin-1 (PFN1) serve as intermodular nodes connecting motor neuron disease pathogenesis and actin cytoskeleton dynamics." (PMID 36341099, 2022). "Furthermore, the protein products for several genes that have been causally linked to ALS are found within the M2 module, including HNRNPA1, MATR3, and PFN1 and TDP‐43 itself, whereas HSPB1 (in M6) has been linked to hereditary motor neuropathy, a form of motor neuron disease." (PMID 29191947, 2018).
neuroblastoma (3 papers, 2015 to 2022). Neuroblastoma (NB) is the most common solid, extracranial childhood tumor. "In neuronal cells, PFN1 mediates the opposite effect: The velocity of growing microtubules is three-fold increased in PFN1-overexpressing N2A neuroblastoma cells." (PMID 34458253, 2021). "Therefore, we generated and confirmed two clonal CRISPR/Cas9 knockout lines (PFN1(-/-)) in immortalized neuroblastoma-2a (N2a) cells that have been successfully used to model features of ALS." (PMID 35666129, 2022).
prostate carcinoma (3 papers, 2013 to 2019). A carcinoma that arises from epithelial cells of the prostate gland. "Profilin 1 with mutations at the C-terminus, transiently expressed in prostate cancer cells PC-3, showed that Tyr139 is important for proper function of profilin 1 as a tumor suppressor." (PMID 26325675, 2015). "Here we present profilin 1, a known tumor suppressor, as a target for cathepsin X carboxypeptidase activity in prostate cancer PC-3 cells." (PMID 23326535, 2013).
renal cell carcinoma (3 papers, 2015 to 2022). "In contrast, profilin-1 was found to be over-expressed in renal cell carcinoma (RCC), indicating its potential as a diagnostic or progression biomarker and a possible target in RCC45." (PMID 26576504, 2015).
autoimmune disease (2 papers, 2022 to 2024). A disorder resulting from loss of function or tissue destruction of an organ or multiple organs, arising from humoral or cellular immune responses of the individual to their own tissue constituents. "The role of the cytoskeletal system, including cofilin, fascin, profilin 1 and other cytoskeletal binding proteins, in autoimmune diseases has been reported." (PMID 35579089, 2022).
brain infarcts (2 papers, 2024 to 2025). "They performed the knockdown of profilin-1 and observed a significant attenuation of brain infarcts and edema." (PMID 41226490, 2025). "Knockdown of PFN1 also significantly attenuated brain infarcts and edema, improved cerebral blood flow and neurological deficits in MCAO-injured mice." (PMID 37971544, 2024).
giant cell tumor (2 papers, 2022 to 2025). A benign, intermediate, or malignant tumor that arises from the bone or soft tissue. "Also, germline mutations in the ZNF687 and PFN1 genes have been associated to severe, early onset, polyostotic PDB with increased susceptibly to neoplastic degeneration, particularly giant cell tumor." (PMID 36035996, 2022).
glioma (2 papers, 2021 to 2023). A benign or malignant brain and spinal cord tumor that arises from glial cells (astrocytes, oligodendrocytes, ependymal cells). "In high-grade gliomas, RYR2, MCHR2, FADS6, HTR2C, CMTM3, APH1A, and PFN1 genes are related to membrane function." (PMID 37239411, 2023). "The top 20 co-expressed neighbors were selected, and the core genes PFN1, CALR, thymosin beta 10 (TMSB10), HLA.A, CD74 (HLADG), HLA.DRA, HLA.B, TUBB, and TUBA1A were found to play pivotal roles in the network, suggesting that immune genes are involved in glioma formation." (PMID 34660294, 2021).
Glucose intolerance (2 papers, 2013 to 2019). Glucose intolerance (GI) can be defined as dysglycemia that comprises both prediabetes and diabetes. "In that report, it was shown that mice haplo-insufficient for profilin-1 are protected from obesity-associated glucose intolerance, highlighting a role for profilin-1 in impaired metabolic function." (PMID 31506540, 2019).
lymph node metastasis (2 papers, 2014 to 2022). "Assessment of the number of PFN1+CD326+ CTCs may be the most valuable indicator for the risk of lymph node metastasis: AUC, 0.92 (95% CI, 0.80–1.00), sensitivity, 85%, and specificity, 96%." (PMID 37226274, 2022). "Within a 12-month follow-up, lymph node metastases were detected in 64.7% (11 patients out of 17) of HNSCC patients with a PFN1 level of more than 0.32 ng/mL before treatment." (PMID 37226274, 2022). "In HNSCC patients with histologically confirmed lymph node metastases (T1–4N1–2M0), the median level of PFN1 in the blood serum was almost two times higher than in patients without regional metastases (T1–4N0M0)." (PMID 37226274, 2022). "Therefore, the assessment of the number of PFN1+CD326+ CTCs in the peripheral blood of HNSCC patients can determine the presence of lymph node metastases with a sensitivity of 85% and a specificity of 96%." (PMID 37226274, 2022). "The increase in the number of PFN1-expressing CTCS in HNSCC patients with lymph node metastases and the dependence of the number of CAP1-containing CTCs on the histotype of the primary tumor may be associated with the acquisition of functional features of CTCs during the progression of HNSCC." (PMID 37226274, 2022). "The number of PFN1+ and CFL1+CD326+ CTCs was positively correlated with lymph node metastases." (PMID 37226274, 2022).
melanoma (2 papers, 2021). A malignant, usually aggressive tumor composed of atypical, neoplastic melanocytes. "Based on correlation analysis between PDC6IP and 83 MTEX proteins differentiating melanoma patients with PD from those with NED/SD, we found four proteins that strongly (ru > 0.7, P < 0.005) associated with PDC6IP, namely HSP90AB1, PFN1, TUBB, and TUBB1." (PMID 33613873, 2021). "Moreover, the manipulation of cellular PFN1 levels also affects microtubule dynamics: Depletion of PFN1 evokes increased microtubule growth in B16f-melanoma cells." (PMID 34458253, 2021). "Hence, the molecular signature of MTEX consisting of PDCD6IP/ALIX, 4 correlated proteins (HSP90AB1, TUBB, TUBB1, and PFN1) highly expressed in MTEX of patients with PD, plus CNTN1 and TGF‐β1 with differential distribution in MTEX of PD vs NED/SD patients may have prognostic significance in melanoma." (PMID 33613873, 2021).
motor neuron degeneration (2 papers, 2012 to 2024). "An increasing body of evidence indicates that TDP-43 proteinopathy underlies motor neuron degeneration caused by diverse genetic defects in various hereditary ALS, including ubiquilin 2, profilin-1, optineurin, valosin-containing protein (VCP), and C9ORF72." (PMID 23300771, 2012). "While PFN1 and SOD1 do not share functional similarities, their mutated forms display comparable patterns in neuropathology, particularly concerning the ongoing progression of motor neuron degeneration (Lim, Kang & Song, 2017)." (PMID 38912047, 2024).
multiple myeloma (2 papers, 2021). "In addition, proteins that stimulate actin polymerization, such as PFN1, have been associated with resistance to the proteasome inhibitor bortezomib in multiple myeloma." (PMID 34172833, 2021).
osteosarcoma (2 papers, 2023 to 2025). A usually aggressive malignant bone-forming mesenchymal neoplasm, predominantly affecting adolescents and young adults. "Accordingly, next-generation sequencing technologies highlighted that Profilin 1 knock-out cells display extensive copy-number alterations, which are associated with complex genome rearrangements and chromothripsis events in primary pagetic osteosarcomas with Profilin 1 inactivation." (PMID 36599901, 2023).
ovarian carcinoma (2 papers, 2009 to 2024). A malignant neoplasm originating from the surface ovarian epithelium. "Literature review found Cofilin 1 (CFL1), Ezrin (EZR), Cyclophilin-A (CYPA), Profilin 1 (PFN1), Napsin A (NAPSA) have been found to be associated with the development and progression of OC15–19, and are potential TAAs for ovarian cancer." (PMID 38684875, 2024). "Increased protein levels for Timp1, Lcn2, Igfbp2, Pfn1, and Sparc were observed in ovarian tumor tissues isolated from K-ras/Pten and Pten/Apc ovarian cancer mouse models compared to control tissue lysates." (PMID 19936259, 2009).
pancreatic adenocarcinoma (2 papers, 2014 to 2017). "Ena/VASP proteins are uniquely linked to Profilin-1 (Pfn1), a G-Actin binding protein that is down regulated in breast, hepatic and pancreatic adenocarcinomas." (PMID 28476046, 2017). "Here, we investigated the exact role of Profilin1 (Pfn1) in pancreatic adenocarcinoma (PDAC) and the underlying mechanisms." (PMID 25103363, 2014). "Pfn1 was downregulated in clinical pancreatic adenocarcinoma specimens compared with the surrounding benign tissues." (PMID 25103363, 2014).
psoriasis (2 papers, 2022 to 2024). An autoimmune condition characterized by red, well-delineated plaques with silvery scales that are usually on the extensor surfaces and scalp. "PFN1/Profilin‐1 was also markedly expressed in the skin and serum of patients with psoriasis, another chronic inflammatory skin disease, and could be used as a biomarker and therapeutic target of psoriasis." (PMID 36305098, 2022).
renal carcinoma (2 papers, 2016 to 2023). A carcinoma arising from the epithelium of the renal parenchyma or the renal pelvis. "Disrupted vasculature in organs (kidney and liver) in Pfn1EC-KO mice is consistent with endothelial Pfn1 dependency for angiogenesis previously shown by our group in early postnatal developmental setting and, more recently, in a tumor angiogenesis setting in a renal cancer model." (PMID 37781098, 2023). "In renal carcinoma, PFN1 levels are increased in the tumor stromal cells, but in normal tissue it is the renal tubule where PFN1 was stained." (PMID 27494863, 2016).
Salmonella Infections (2 papers, 2025). Infections with bacteria of the genus SALMONELLA. "Furthermore, CYRIB is involved in the regulation of memory T cell activation, and PFN1 is involved in the Rap1 signaling pathway, regulation of the actin cytoskeleton, and response to salmonella infection." (PMID 41026719, 2025).
Achalasia (1 paper, 2023). A disorder of esophageal motility characterized by the inability of the lower esophageal sphincter to relax during swallowing and by inadequate or lacking peristalsis in the lower half of the body of the esophagus. "In this study, 164 serum proteins changed significantly in achalasia patients among which the most significantly changed proteins were profilin-1, immunoglobulin heavy variable 3–9, transgelin-2, vasodilator-stimulated phosphoprotein, and galectin-10 (all were upregulated)." (PMID 37324545, 2023).
airway hyperresponsiveness (1 paper, 2023). "PFN1 may also be crucial for viral transcriptional activation and airway hyperresponsiveness." (PMID 37007947, 2023).
Anxiety (1 paper, 2025). Intense feelings of nervousness, tension, or panic often arise in response to interpersonal stresses. "Previous studies have demonstrated a relation between PFN1 levels and ovarian function, however the relationship between PFN1 and psychophysiological anxiety has not been previously investigated." (PMID 39920522, 2025).
aortic aneurysm (1 paper, 2025). A ruptured aneurysm located in the wall of the proximal portion of the descending aorta proceeding from the arch of the aorta. "In their study, profilin 1 (PFN1) and complement factor D (CFD) were found to be two potential new biomarkers for the diagnosis of aortic aneurysms, and their combination could improve the diagnosis rate of aortic aneurysms." (PMID 40599317, 2025).
Aortic dissection (1 paper, 2023). Aortic dissection refers to a tear in the intimal layer of the aorta causing a separation between the intima and the medial layers of the aorta. "The serum concentrations of PFN1 and CFD also showed significant differences between patients with aortic dissection and controls in the validation study." (PMID 37543598, 2023). "We also measured the serum levels of PFN1 and CFD in patients with aortic dissection (AD) in the validation study to investigate their applications in other related diseases." (PMID 37543598, 2023).
asthma (1 paper, 2022). "Many genes, including Il33, Cxcl5, Cxcl15, Ccl20, Cxcl3, Cxcl1, C3, and Pfn1, which have been linked to asthma pathogenesis, showed a cell type-specific response to HDM." (PMID 35627266, 2022).
bronchopulmonary dysplasia (1 paper, 2021). Bronchopulmonary dysplasia is a chronic respiratory disease that results from complications related to lung injury during the treatment of infant acute respiratory distress syndrome in low-birth-weight premature infants or from abnormal lung development in older infants. "Studies have examined lower profilin-1 and elevated cofilin-1 levels observed in infant bronchopulmonary dysplasia (BPD) tissue." (PMID 34194957, 2021). "A study about infants born prematurely with bronchopulmonary dysplasia (BPD) found that highly expressed Tβ4 and profilin-1 are detected in lung epithelial cells." (PMID 34194957, 2021).
Cerebral ischemia (1 paper, 2020). Restriction of arterial blood supply to the brain associated with insufficient oxygenation to support the metabolic requirements of the tissue. "In a recent study, the depletion of profilin-1 (Pfn1), which is an actin-binding protein involved in the dynamic transformation and reorganization of cytoskeleton, attenuated damage upon cerebral ischemia via modulation of microglial cell function associated with the RHOA/ROCK pathway." (PMID 33071819, 2020).
cognitive deficits (1 paper, 2019). "Therefore, impairments in signaling pathways that regulate synaptic markers such as PSD-95 and synaptophysin, and actin dynamics, such as profilin-1, could lead to the synaptic and cognitive deficits observed early in AD." (PMID 31685865, 2019).
colon cancer (1 paper, 2005). "For example, what is the role of profilin 1 protein in colon cancer?" (PMID 15784140, 2005).
corneal ulcer (1 paper, 2022). Area of epithelial tissue loss from corneal surface; associated with inflammatory cells in the cornea and anterior chamber. "Profilin 1 and cofilin expression was particularly elevated in the case of viral keratitis and fungal keratitis compared to corneal ulcers." (PMID 35269714, 2022).
coronary artery disease (1 paper, 2021). "A growing amount of data associate profilin 1, a protein crucial for cell biology, with the pathogenesis of coronary artery disease." (PMID 33499277, 2021).
coronary atherosclerosis (1 paper, 2010). Atherosclerosis of the coronary vasculature. "Nevertheless, the association between profilin-1 levels and coronary atherosclerosis should be analyzed in a larger cohort of patients in future studies." (PMID 21049052, 2010).
DNA repair disorders (1 paper, 2021). "Future studies addressing the crosstalk and regulation of PTEN-related DNA damage sensing and repair pathway choice by PFN1 may further aid to identify new mechanistic insights for various DNA repair disorders." (PMID 33590416, 2021).
dry eye (1 paper, 2019). "GSN and PFN1 have also been shown to be upregulated particularly in aqueous-deficient dry eye with and without lipid deficiency, but not in lipid-deficient dry eye alone." (PMID 30976209, 2019).
dwarfism (1 paper, 2024). "Previous studies demonstrated that disturbances in the levels of profilin-1, the protein encoded by PFN1, have been detected in individuals with skeletal disorders, such as dwarfism, facial deformities, and altered bone structure and size." (PMID 39769211, 2024).
glomerulosclerosis (1 paper, 2023). A hardening of the kidney glomerulus caused by scarring of the blood vessels. "Given the observation that Pfn1-KO podocytes exhibited MC, podocyte loss, glomerulosclerosis, and kidney failure, we next aimed to understand the potential mechanism underlying this observed phenotype." (PMID 37847555, 2023). "Loss of podocyte-specific Pfn1 results in glomerulosclerosis, tubulointerstitial injury, and foot process effacement." (PMID 37847555, 2023). "To further determine the impact of Pfn1 in podocytes, we generated podocyte-specific Pfn1-KO mice, which revealed severe proteinuria, glomerulosclerosis, and kidney failure." (PMID 37847555, 2023).
head and neck squamous cell carcinoma (1 paper, 2022). A squamous cell carcinoma that arises from any of the following anatomic sites: lip and oral cavity, nasal cavity, paranasal sinuses, pharynx, larynx, and salivary glands. "Actin-binding proteins, including cofilin (CFL1), profilin 1 (PFN1), and adenylate cyclase-associated protein 1 (CAP1), are thought to be involved in tumor cell motility and metastasis, specifically in head and neck squamous cell carcinoma (HNSCC)." (PMID 37226274, 2022).
HIV-1 infection (1 paper, 2012). The type species of lentivirus and the etiologic agent of acquired immunodeficiency syndrome (AIDS). "The mechanism by which these proteins are down-regulated remains to be investigated, but the up-regulation of mRNA (but not protein) for Rho-GDI and profilin-1 during HIV-1 infection could indicate impairment in protein translation induced by the virus." (PMID 22958358, 2012).